BRCA1 (BRCA1 DNA repair associated)
Diseases named in the same sentence as BRCA1 in open-access papers (continued):
Sharing a sentence is not in itself a finding about the gene and the disease.
cancer (continued). "As to the question of how cancer arises in cells with deficiencies in BRCA1 or BRCA2, it seems likely that the impaired function of HR is a key step, since this is the only established defect in BRCA2-deficient cells." (PMID 15054444, 2004). "Four cases showed concordant loss of BRCA1 alleles in left and right cancers, four for BRCA2, seven for ATM and four cases for FHIT, suggesting possible roles for these tumour suppressor genes." (PMID 12771912, 2003). "While prophylactic surgery is still somewhat controversial, evidence suggests that risk is significantly reduced for women at high risk and therefore offers hope that their risk of cancer will be reduced despite the presence of the BRCA1/2 mutation." (PMID 11953874, 2002). "Predictive genetic testing is available to some individuals unaffected with cancer where a BRCA1/2 mutation has been identified in the family." (PMID 11953874, 2002). "Cancer patients with BRCA1 or BRCA2 germline mutations are sensitive to PARPi." (PMID 41510186, 2026). "Furthermore, a cancer-promoting program activated by BRCA1 mutation was vulnerable to histone deacetylase inhibitors, which inhibited LUAD tumor growth." (PMID 42189716, 2026). "Women carrying a BRCA1 mutation and those with a diagnosed cancer were excluded from the study." (PMID 41828619, 2026). "Small molecule inhibitors of PARP are used to treat cancers with BRCA1 or BRCA2 mutations." (PMID 41326692, 2026). "However, the reason LPs are prone to transform into cancer cells when BRCA1 is deficient is unclear." (PMID 41498327, 2026). "The detection of BRCA1/2 variants in off-tumor patients, for example, may inform cancer surveillance strategies for other related cancers and contribute to family health management." (PMID 40926019, 2026). "In the UK, cancer genetic testing is primarily conducted through targeted panels that focus on specific cancer types or known genetic mutations associated with particular cancers, such as BRCA1 and BRCA2 mutations for breast and ovarian cancers." (PMID 41206382, 2026). "These include cancers in patients with BRCA1 or BRCA2 mutations." (PMID 41537447, 2026). "Indeed, the actual risk of new cancer or cancer recurrence of patients carrying the BRCA1/2 mutation gene can be quantified, which allows personalized management." (PMID 40338860, 2025). "Precise estimates could inform cancer surveillance and risk-reduction options for survivors of BC carrying BRCA1/BRCA2 PVs." (PMID 39475295, 2025). "Broader exome-wide analyses comparing affected vs. unaffected BRCA1/2 mutation carriers, or women stratified by age at cancer onset, could help identify additional genetic modifiers of cancer risk." (PMID 41374957, 2025). "Of those heritable cancers, 30% are caused by germline BRCA1/2 mutations." (PMID 39235712, 2025). "In addition to the upregulated Il11 and Il1rn, which were notably lowly transcribed in early passage deermouse cells in comparison to mouse cells, two cancer-associated genes, Brca1 and Myc, were more highly transcribed in P47 than in P4 cells." (PMID 41262241, 2025). "BRCA1 mutation carriers are more likely than the general population to develop these cancers." (PMID 40141415, 2025). "Further, BRCA1 was linked to the homologous recombination pathway across cancer types." (PMID 41186627, 2025). "Future research should focus on obtaining baseline PROM scores and assessing the long-term effect and variation of different risk management strategies on quality-of-life and body image outcomes, to better assist carriers of P/LP variants in BRCA1/2 genes regarding their cancer risk management." (PMID 40445415, 2025). "The broader gene analysis was driven by the possibility of misclassified primary tumours and increasing evidence that genes associated with other cancers (e.g., BRCA1, BRCA2, CHEK2) may also influence CRC risk through shared pathways." (PMID 40627234, 2025).
cancer (continued). "Consequently, the inhibition of PARPs has emerged as a therapeutic strategy aimed at BRCA1/2-mutated cancer cells." (PMID 41219748, 2025). "This also means that a single inherited cancer syndrome can predispose individuals to a broader spectrum of tumors than initially thought (for example, still speaking of BRCA1/2 mutations, they primarily cause breast and ovarian cancers, but they can also increase the risk of other cancers)." (PMID 40647400, 2025). "The rationale of this combination comes from the hypothesis that PARP inhibition in BRCA1/2 mutated cancer cells may elicit genomic instability, generating DNA fragments able to activate the intracellular stimulator of interferon genes pathway." (PMID 40941037, 2025). "It is worth noting that these assays were predominantly commercial, with the Myriad MyChoice® CDx kit being the most prevalent at 46%, followed closely by Myriad BRACAnalysis® CDx at 40%, FoundationOne® CDx at 17%, and the BROCA Cancer Risk Panel at 6% of the studies that looked at BRCA1/2." (PMID 40069561, 2025). "The elevated CBC/OC cancer risks, together with previous results, suggest that females found to carry BRCA1/BRCA2 PVs may wish to consider risk-reducing options such as contralateral mastectomy and risk-reducing bilateral salpingo-oophorectomy after BC." (PMID 39475295, 2025). "List of pathogenic variants of BRCA1/2 and the number of cancer types." (PMID 40249378, 2025). "PARPis not only improve the treatment outcome of patients with BRCA1/2-mutated cancers but also, as our understanding of HRD and BRCAness has increased, more patients may benefit from these therapies." (PMID 40521389, 2025). "Accordingly, five milligrams of PB was required to destroy half of the BRCA1‐blocked cells, suggesting that PB may be a helpful therapeutic intervention for cancers caused by BRCA1 mutations." (PMID 40842665, 2025). "This may indicate BRCA1 deficient cancer cells benefit from a decrease in TLK even when the cells are not receiving PARPi." (PMID 39844055, 2025). "Studies have shown genetic testing can improve survival rates in patients diagnosed with cancer by guiding decisions on prophylactic surgeries such as bilateral mastectomy and oophorectomy and enabling personalized treatment with targeted cancer therapies for BRCA1/2 mutation carriers." (PMID 40405031, 2025). "Thus, studies characterizing ER/PR/HER2-negative cells carrying a BRCA1 germline mutation are needed to gain more in-depth knowledge about the steps leading to cancer initiation in BRCA1 carriers." (PMID 41283387, 2025). "This case report could be understood as an indication that BRCA1 mutation is not only important in the “classic BRCA1 entities” but also represents a general influencing factor in cancer therapy." (PMID 40519304, 2025). "These insights lay the groundworkfor future studies examining how cancer-associated variants affectthe DNA binding and repair phenotypes of BRCA1 and may inform theinterpretation of variants of unknown clinical significance." (PMID 40903918, 2025). "Our findings have relevance to immune response in patients with BRCA1-linked cancer." (PMID 41347767, 2025). "Note that this care provision may change with recent shifts towards introducing population‐based genetic testing for BRCA1/2 and other variants related to cancer risk." (PMID 39812114, 2025). "The reduction in radiographic progression is clinically significant, most notably in cancers with a BRCA1/2 mutation, and this combination could represent a new treatment option for such patients." (PMID 41057655, 2025). "A significant portion of cases of OC, accounting for more than 20%, appears to be associated with monogenic cancer susceptibility conditions, of which the majority (up to 90%) is due to heterozygous pathogenic or likely pathogenic (P/LP) variants in the BRCA1/2 (BRCA) genes." (PMID 39984762, 2025).
cancer (continued). "Interestingly, patients with BRCA1/2 biallelic alterations exhibited higher HRD scores than others with oHRR biallelic alterations (P<0.001), highlighting the greater impact of BRCA1/2 on HRD in BRCA-associated cancers." (PMID 40420266, 2025). "Monotherapy in HR-deficient tumors: In BRCA1/2- or related repair-deficient cancers, APE2 loss is synthetically lethal, so an APE2 drug could be effective on its own." (PMID 41446759, 2025). "BRCA1 is established as a risk gene for several cancers in adult age, but alterations in BRCA1 function may also influence risk of cancer in younger ages." (PMID 39724532, 2025). "The LIBRE study is a randomized controlled trial designed to evaluate whether lifestyle interventions can modulate cancer-related risk factors in women with germline BRCA1/2 mutations." (PMID 40731797, 2025). "Mechanistically, PDIK1L’s interaction with nucleotide biosynthesis pathways could deplete dNTP pools, exacerbating replication stress and genomic instability in C2 tumors—a phenomenon observed in BRCA1-deficient cancers treated with PARPi." (PMID 41262299, 2025). "Women with BRCA1/2 mutations can opt for prophylactic surgeries (such as mastectomy and salpingo-oophorectomy), chemoprevention, and intensive breast imaging surveillance to reduce their cancer risk." (PMID 40567951, 2025). "Although preclinical and clinical trials have shown that PARP inhibitors are effective for BRCA1-associated cancers, some limitations to the synthetic lethality approach still exist, such as evidence for therapeutic efficacy, side effects, and resistance to PARP inhibitors." (PMID 41155174, 2025). "Further systematic exome-wide comparisons between affected and unaffected BRCA1/2 heterozygotes, or between young-onset and late-onset BRCA1/2-driven cancer cases, are required to reveal novel genetic determinants which influence cancer risk BRCA1/2 mutation carriers." (PMID 41374957, 2025). "Even though the age of cancer diagnosis varies, patients with BRCA mutations seem to have a lower age of cancer diagnosis when compared to the general population of patients, with the mean age of cancer diagnosis being around 51 years for BRCA1 patients and 61 years for BRCA2 patients." (PMID 40869932, 2025). "PARP inhibitors (olaparib, rucaparib, niraparib, and talazoparib) are a prime example of precision medicine, as they selectively target cancer cells with DNA repair deficiencies, such as BRCA1/2 mutations, leading to increased genomic instability and cell death." (PMID 41373813, 2025). "Interestingly, TCGA data analysis on cancers that were not treated with PARPi suggests that a decrease in TLK kinases predicts poor outcome in BRCA1 deficient tumors, while it often predicts the opposite in BRCA1 proficient cancers." (PMID 39844055, 2025). "In addition to these established cancer risks, a growing body of clinical data suggests BRCA1 and BRCA2 carriers also have an increased risk of GC." (PMID 41256354, 2025). "Study indicate that certain gene mutations (e.g., BRCA1/2) are closely associated with the risk of specific cancers in women, which may further influence MPMN incidence." (PMID 41584579, 2025). "This differential sensitivity likely reflects underlying tumor biology: BRCA1-associated cancers are more frequently triple-negative and characterized by a high proliferative index, genomic instability, and basal-like transcriptional profiles, all features linked to heightened chemosensitivity." (PMID 41463210, 2025). "Considering that BRCA1 mutations contribute to TNBC development, personalized preventative cancer vaccines for individuals with germline BRCA1 mutation could be beneficial." (PMID 40573960, 2025). "Although studies on the impact of environmental and lifestyle variables on cancer are ongoing, there is little proof to support that they might produce BRCA1 or BRCA2 mutations on their own." (PMID 40141415, 2025).
cancer (continued). "The United Kingdom Biobank study analysis found that the average cancer risk appeared to be lower in germline carriers in the biobank as compared to the BRCA1/2 carriers with a positive family history, suggesting that the nature of the variant and/or the genetic background modifies risk." (PMID 40747594, 2025). "However, in cancers with BRCA1/2 mutations, homologous recombination is impaired, forcing cells to depend on less accurate and alternative DNA repair mechanisms, such as PARP-mediated repair, which makes them particularly susceptible to PARP inhibition." (PMID 40723906, 2025). "Current efforts are underway to link phenotypes in large pedigreed rhesus macaque colonies to full length DNA sequences to detect naturally occurring genetic variations that may be inherited risk factors for cancer, such as BRCA1/2 mutations in humans." (PMID 39787126, 2025). "These candidate neoantigens may be used to develop a preventive cancer vaccine in BRCA1-mutated carriers after validating their antigenicity and assessment of their ability to regulate cancer progression." (PMID 40437549, 2025). "Notably, there is a paucity of data to assess the impact on the BC risk of BBD in women classified as high-risk based on family history, PV carrier status in a cancer susceptibility gene (mainly BRCA1 and BRCA2), or polygenic risk score (PRS)." (PMID 40694193, 2025). "In our series of 144 patients with early TNBC previously tested WT for the presence of germline variants in the coding regions of BRCA1/2 and other cancer predisposition genes, all patients were found to have at least one rare variant in the promoter regions of 28 BC predisposition genes." (PMID 40338220, 2025). "Certain mutations resulting from these error-prone repair processes may contribute to cancer onset or progression, which helps explain, at least in part, the elevated cancer risk associated with BRCA1 and BRCA2 mutations." (PMID 41373813, 2025). "Furthermore, research has shown that women carrying pathogenic BRCA1/2 gene mutations have up to an 87% risk of developing related cancers." (PMID 40007994, 2025). "In addition, it has been reported that cellular resistance to platinum drugs and PARP inhibitors in BRCA1-defective cancer cells is caused by overexpression of a microRNA(miR-622)-mediated regulation of NHEJ." (PMID 41155174, 2025). "With certain hereditary syndromes, there is also the possibility that cancer survivors may require prophylactic surgeries depending on the evolution of the cancer (e.g., prophylactic salpingo-oophorectomy after a diagnosis of BRCA1/2 mutated breast cancer)." (PMID 38976210, 2025). "The higher mastectomy rates in BRCA1 PV carriers may reflect both the aggressive nature of their tumors and the proactive surgical decision to reduce future cancer risk." (PMID 40422528, 2025). "Hence, aberrations within the HRR pathway, particularly germline or somatic deleterious mutations in Breast cancer gene-1 (BRCA1) BRCA1 or Breast cancer gene-2(BRCA2), can result in synthetic lethality in the presence of PARP inhibitors." (PMID 39333696, 2025). "RBBP7 can specifically bind to the BRCT domain of BRCA1 and modulate its transcriptional activity to influence the regulation of cell proliferation and differentiation, and have been implicated in numerous cancers." (PMID 40688406, 2025). "PARP inhibitors are effective in cancer patients with BRCA1 mutations but whether this can extend to BRCA1 wildtype patients by targeting BRCA1 transcriptional regulation is unclear." (PMID 40764600, 2025). "HR deficiency, such as in BRCA1/2-mutated cancer cells confers synthetic lethality to PARPi." (PMID 41243969, 2025).
cancer (continued). "For example, reversion mutations or epigenetic alterations leading to the re‐expression of a BRCA1 or BRCA2 wild‐type protein or resulting in hypomorphic variants are common resistance mechanisms to PARPi, which is also the main mechanism for platinum resistance in BRCA1/2‐mutated cancer." (PMID 40980974, 2025). "Genetic studies in Latin America have expanded, but further efforts are needed to understand cancer susceptibility genes beyond BRCA1 and BRCA2, especially by characterizing the prevalence and spectrum of pathogenic or likely pathogenic variants (PVs) in the region." (PMID 40065011, 2025). "While BRCA2-associated cancers are predominantly hormone receptor-positive tumors, BRCA1-associated tumors are more frequently classified as triple-negative breast cancer (TNBC), a subtype known for its aggressive nature and higher sensitivity to neoadjuvant chemotherapy." (PMID 40422528, 2025). "This means that annual surveillance for the gastrointestinal tract might be considered for BRCA1 or 2 mutated cancers." (PMID 39996890, 2025). "Our findings suggest that rare genetic variations may play a role in modulating cancer risk among BRCA1/2 mutation carriers, underscoring the potential value of including these variants in future analyses." (PMID 41374957, 2025). "Conversely, pharmacological activation of TET enzymes using Vitamin C leading to global increase in 5hmC levels can exacerbate PARP trapping at sites of DNA damage, effectively restoring sensitivity to PARPi in chemoresistant cancer cells, particularly those harboring BRCA1 or BRCA2 deficiencies." (PMID 41243111, 2025). "Regarding HR deficiency, recent work has shown that BRCA1-deficiency may be important to the response of cancer cells co-treated with a GPX4 and PARP combination, where GPX4 inhibition can induce ferroptosis." (PMID 40568132, 2025). "These somatic mutation signatures may serve as neoantigens for generating vaccines that may target BRCA1/2 deficient cancers." (PMID 40437549, 2025). "Subthemes arising under this theme were: general cancer risks and management options (7/19, 36.8%), cancer risks based on family history/ancestry (4/19, 21.1%), insurance (4/19, 21.1%), other genes beyond BRCA1/BRCA2/PALB2 (3/19, 15.8%) and variants of uncertain significance (1/19, 5.3%)." (PMID 40081871, 2025). "Therefore, FEN1 or DNA2 inhibitors can induce synthetic lethality with BRCA1/2 deficiency and/or with PARPi in human cancer cells." (PMID 38714348, 2024). "Our recent work suggests that the miRNA profile could be associated with states linked to an increased risk of cancer development, such as BRCA1/2 mutation or exposure to risk factors like ionizing radiation." (PMID 38983926, 2024). "Each of the groups displayed different number of methylation changes, with BRCA1 epimutation carriers harboring the highest number of 5163 differently methylated CpG sites, germline mutation carriers 2473 CpG sites, and cancer free women, who developed cancer after follow up, 12 CpG sites." (PMID 39529133, 2024). "And loss of PARG, induced olaparib resistance in BRCA1- or BRCA2-deleted cancer cells." (PMID 38625917, 2024). "Although PARPi have achieved great success in treating patients with BRCA1/2 mutated cancers, the current application of PARPi still faces some challenges, especially in improving the efficacy of PARPi in BRCA1/2 wild-type cancer patients and overcoming acquired resistance to PARPi." (PMID 39156700, 2024). "Finally, we discuss how targeting this newly discovered pathway specifically affects cell survival in BRCA1-deficient cancer cells." (PMID 38943334, 2024).